ITGAV (integrin subunit alpha V)
Diseases named in the same sentence as ITGAV in open-access papers (continued):
Sharing a sentence is not in itself a finding about the gene and the disease.
colitis (7 papers, 2022 to 2025). Inflammation of the colon. "Here, we report ITGAV variants in patients with brain defects and colitis and provide insight into the pathogenesis." (PMID 39526957, 2024). "Furthermore, very-early-onset colitis and brain abnormalities have been described in three families harboring an integrin alpha-v variant (ITGAV) and in a patient with homozygous integrin β-6 polymorphism (ITGB6)." (PMID 40918109, 2025). "For example, mice bearing a conditional knockout of ITGAV in myeloid cells and αVβ8 specifically in dendritic cells develop severe colitis, demonstrating an important protective function of the integrin in innate immune cells of the gut." (PMID 39526957, 2024). "Taken together, the ITGAV variants identified in this report caused a previously unknown human disease characterized by brain and developmental defects in the case of complete loss-of-function and atopy, neurodevelopmental defects, and colitis in cases of incomplete loss-of-function." (PMID 39526957, 2024). "Many of the defects in ITGAV-null mice, in fact, phenocopy observations made in patients with loss-of-function variants in TGFB1, which also have brain defects and colitis for example." (PMID 39526957, 2024). "Defects in TGF-beta processing and signaling (e.g., ITGAV), especially in dendritic cells, can trigger colitis." (PMID 36140740, 2022).
esophageal cancer (7 papers, 2017 to 2025). A primary or metastatic malignant neoplasm involving the esophagus. "Numerous studies have demonstrated that WDHD1 can affect the growth of esophageal cancer by regulating the PI3K/AKT pathway during the cell cycle, WDHD1 in nasopharyngeal cancer, and ITGAV in the management of the NPC cell cycle." (PMID 38980253, 2024). "The methylation levels of APC, ITGAV, PRDM16 and PTX3 were significantly different between esophageal cancer and healthy control tissues." (PMID 27893424, 2017).
lymph node metastasis (7 papers, 2015 to 2022). "ITGB1 expression was associated with presence of lymph node metastasis (P = 0.039) and Integrin alpha V (ITGAV) expression (P < 0.001)." (PMID 36456612, 2022). "The low expression of the proteins LTA4H, PGK1, NDRG1, COL6A1, and ITGAV in the saliva samples was associated with lymph node metastasis and advanced clinical staging (crosstabulation and chi-square test, P value < 0.05)." (PMID 30185791, 2018). "The findings of our multivariate model also correlate with the results of previous univariate studies that have described an association between the ITGAV integrin and the presence of distant metastases, lymph node metastases, and perineural invasion." (PMID 26674523, 2015). "A multivariate cox-regression model was performed which showed tumor stage, lymph node metastasis and ITGAV expression as independent prognostic markers for overall-survival in the group of patients without neoadjuvant treatment." (PMID 33110104, 2020). "Interestingly, SRM-MS analysis showed CSTB, LTA4H, PGK1, COL6A1, ITGAV, and NDRG1 were significantly downregulated in patients with lymph node metastasis." (PMID 30185791, 2018).
pancreatic adenocarcinoma (7 papers, 2018 to 2025). "For example, cholangiocarcinoma (CHOL) overexpresses a large variety of subunits (e.g. ITGAV, ITGA1, ITGA4, ITGA5, ITGA11, ITGB1, ITGB2, ITGB6), whereas, the equally deadly pancreatic adenocarcinoma (PAAD) overexpresses a very limited set of integrins, including ITGA6 and ITGB4." (PMID 30046394, 2018).
cholangiocarcinoma (6 papers, 2018 to 2025). A carcinoma that arises from the intrahepatic biliary tree (intrahepatic cholangiocarcinoma) or from the junction, or adjacent to the junction, of the right and left hepatic ducts (hilar cholangiocarcinoma). "Also reported in the literature, ITGAV can promote the progression of cholangiocarcinoma (CCA) by affecting the infiltration of neutrophils." (PMID 40018050, 2025). "In this study, analysis of both TCGA and GEO datasets revealed a significantly upregulated gene expression of ITGAV in HNSCC and various cancers, such as cholangiocarcinoma (CHOL), liver hepatocellular carcinoma (LIHC), lung squamous cell carcinoma (LUSC), and stomach adenocarcinoma (STAD)." (PMID 38534932, 2024).
head and neck squamous cell carcinoma (6 papers, 2022 to 2025). A squamous cell carcinoma that arises from any of the following anatomic sites: lip and oral cavity, nasal cavity, paranasal sinuses, pharynx, larynx, and salivary glands. "Moreover, the high expression of ITGAV was closed associated with the lower overall survival of human cancer like head and neck squamous cell carcinoma, which was considered as a valuable biomarker in clinical." (PMID 41415585, 2025). "ITGAV, a subunit of αv integrins, plays a crucial role in extracellular matrix remodeling and signal transduction, and its overexpression has been linked to epithelial–mesenchymal transition (EMT) and poor prognosis in various malignancies, including head and neck squamous cell carcinoma." (PMID 41356699, 2025).
lung adenocarcinoma (6 papers, 2018 to 2025). A carcinoma that arises from the lung and is characterized by the presence of malignant glandular epithelial cells. "RNA data from the database TCGA showed that mRNA expression of ITGAV and ITGB3 correlated positively with SPP1 expression in lung adenocarcinoma and squamous patients." (PMID 33287873, 2020).
mesothelioma (6 papers, 2022 to 2025). A usually malignant and aggressive neoplasm of the mesothelium which is often associated with exposure to asbestos. "We first evaluated the expression of EMT molecules, which have been associated with prognosis in patients with mesothelioma, including Zeb1, YAP, ITGAV, and ACTA2." (PMID 40396518, 2025). "The top four genes (COL5A2, ITGAV, SPARC, and ACTA2) associated with the strongest correlation with EMT Top50 mesenchymal genes were selected for further analysis, confirming their prognostic importance in mesothelioma and other solid tumors using the TCGA database of online platforms." (PMID 36901697, 2023). "Xenoplanted D‐Meso‐Sonobe cells expressed nuclear Zeb1 and yes‐associated protein at the cancer invasion front and focally expressed integrin subunit alpha V and actin alpha 2, which are molecular phenotypes acquired by EMT in mesothelioma." (PMID 40396518, 2025). "ITGAV and ACTA2 are representative EMT‐related proteins in mesothelioma." (PMID 40396518, 2025). "Among these cancers, ITGAV has been identified as a risk factor in LIHC, mesothelioma, and PAAD, while no reports about the remaining six cancers indicated the novelty of our study." (PMID 35927660, 2022). "Furthermore, it might be of interest to investigate the contribution of RNA editing in the increased expression of COL5A2, ITGAV, and SPARC genes, which is correlated with mesenchymal phenotype in mesothelioma." (PMID 36769192, 2023). "Besides a few sporadic studies, this may be the first study to identify COL5A2, ITGAV SPARC and ACTA2 as a panel of emerging EMT genes in mesothelioma." (PMID 35046456, 2022).
nasopharyngeal carcinoma (6 papers, 2019 to 2026). A carcinoma arising from the nasopharyngeal epithelium. "It has also been reported that miR-9–3p can inhibit epithelial-mesenchymal transition by down-regulating ITGB1, FN1, and ITGAV in nasopharyngeal carcinoma." (PMID 31164410, 2019). "Comprehensive analysis showed that WDHD1 is highly expressed in nasopharyngeal carcinoma (NPC) tissues, and it may affect cell apoptosis by regulating the expression of ITGAV." (PMID 36345604, 2023).
osteosarcoma (6 papers, 2020 to 2025). A usually aggressive malignant bone-forming mesenchymal neoplasm, predominantly affecting adolescents and young adults. "Likewise, miR-548c-3p has been reported as a tumor suppressor miRNA in osteosarcoma subjects through targeting ITGAV, alleviating cell proliferation." (PMID 38627665, 2024). "Meanwhile, some hub genes have been reported involved in the tumorigenesis and progression of osteosarcoma, such as ITGAV, POSTN, COL1A1, TGFB1, TGFB3, and ITGAV." (PMID 32582282, 2020).
bladder cancer (5 papers, 2014 to 2025). "ITGAV knockout mice promoted skin cancer development and ITGAV expression was positively associated with cancer cell stemness and tumorigenesis in prostate and bladder cancer." (PMID 30486830, 2018). "In this study, the role of ITGAV, which are highly expressed in bladder carcinomas, and its potential as a drug target in bladder cancer were investigated both by treatment with the ITGAV integrin-inhibitor GLPG0187 and knockdown of ITGAV." (PMID 25247809, 2014). "Functional inactivation of ITGAV in bladder cancer leads to a less malignant phenotype as illustrated by significantly impaired migration, EMT response, clonogenicity and a reduction in the size of the stem/progenitor pool." (PMID 25247809, 2014). "It is also noteworthy that inhibition of ITGAV reduced prostate and bladder cancer stemness and these results may be related with integrin-mediated NF-κB signaling." (PMID 30486830, 2018). "Moreover, during EMT, epithelial markers such as ITGAV (αv integrin receptors) are upregulated in several solid tumours, including bladder cancer with a trend increase in ITGAV expression with disease stage and grade." (PMID 29207682, 2017). "ITGAV expression was significantly higher in stage IV and III bladder cancer (BLCA) patients than in stage II bladder cancer patients." (PMID 40775249, 2025). "ITGAV knockdown and ITGAV antagonist treatment reduced cell migration, stemness, and EMT in prostate and bladder cancer." (PMID 30486830, 2018). "Previous studies have shown that the inhibition of ITGAV expression decreased cancer stemness, migration and EMT in bladder carcinoma cells." (PMID 30486830, 2018). "Inhibition of αv integrin might also have therapeutic potential in bladder cancer, since ITGAV is significantly overexpressed in bladder tumors (46%) compared to normal urothelium (13%) and a trend is observed of stage and grade-dependent increase in ITGAV expression." (PMID 25247809, 2014). "Additionally, SPP1 can also recognize albumin (ALB), integrin-A (ITGAV) and integrin-B (ITGB1) proteins whose expression was found to be highly increased at an early stage of bladder cancer development, using the TCGA-BLCA search engine." (PMID 38067407, 2023). "In the present study we determined the effect of functional inactivation of ITGAV (targeting with GLPG0187 or knockdown of ITGAV) on migration, EMT and stemness in bladder cancer using the human bladder carcinoma cell line UM-UC-3 and the human papilloma cell line RT-4." (PMID 25247809, 2014). "Since knockdown of ITGAV and to a lesser extent treatment with the GLPG0187 compound in UM-UC-3 and RT-4 cells resulted in a significant decrease in SNAI2, SNAI2 might play an important role in EMT in bladder cancer." (PMID 25247809, 2014).
colon carcinoma (5 papers, 2018 to 2024).
esophageal adenocarcinoma (5 papers, 2020 to 2024). A malignant tumor with glandular differentiation arising predominantly from Barrett mucosa in the lower third of the esophagus. "The expression pattern and biological role of ITGAV expression in esophageal adenocarcinoma (EAC) has not been analyzed so far." (PMID 33110104, 2020). "However, the expression pattern and biological role of ITGAV expression in esophageal adenocarcinoma (EAC) has not been analysed so far." (PMID 33110104, 2020).
gastric adenocarcinoma (5 papers, 2022 to 2025). "In summary, molecules such as DKK1, GHRL, STC1, NRP1 and ITGAV play important roles in the development and prognosis of gastric adenocarcinoma." (PMID 38752750, 2024). "Moreover, patients with gastric adenocarcinoma had the highest frequency of ITGAV gene alterations among the deep deletion types." (PMID 40018050, 2025). "ITGAV (Integrin Alpha V) is a protein that is overexpressed in gastric adenocarcinoma." (PMID 38752750, 2024).
liver fibrosis (5 papers, 2016 to 2025). "The upregulated genes including VCAN and ITGAV by HBV-SITE-1 are both novel biomarkers of hepatitis B virus-related liver fibrosis." (PMID 40405227, 2025). "Experimental evidence demonstrates that depletion of the ITGAV subunit in HSCs protects mice from liver fibrosis induced by CCl4." (PMID 36313326, 2022). "ITGAV, namely αV integrins, are heterodimeric cell-surface proteins, that play a central role in the progression of liver fibrosis as they activate latent TGF-β which is a known profibrogenic cytokine." (PMID 36313326, 2022). "Combined with the GO, KEGG and Western blot results, COL1A2, ITGAV, TLR2, ACE, and PDGFRB may be potential targets for PE treatment of liver fibrosis." (PMID 36313326, 2022). "ITGAV and PDGFRA are two genes up-regulated, which could promote hepatic fibrosis." (PMID 38549107, 2024).
inflammatory bowel disease (4 papers, 2022 to 2025). A spectrum of small and large bowel inflammatory diseases of unknown etiology. "For example, male-specific pQTL rs3213946 is also eQTL for several genes (ITGAV, FAM171B, ATP6V1B2 and ZC3H15) and associated with diseases such as inflammatory bowel disease, coronary artery disease, and attention deficit hyperactivity disorder." (PMID 38326779, 2024). "While these CP-related findings differ from intestinal CD, we could detect a higher abundance of predictive protein markers for anti-TNF-α therapy in CD esophagitis as described in serum of inflammatory bowel disease (IBD) patients such as CRP, ITGAV, APOE, and CLU (Fig. EV4C)." (PMID 39901020, 2025).
liver cancer (4 papers, 2018 to 2025). An epithelial or non-epithelial malignant neoplasm that arises from the liver. "Based on 4 genes (COMP, SPP1, COL4A2, and ITGAV) in the pathway of integrin cell surface interactions, a risk score model for prognosis of liver cancer was constructed." (PMID 38374893, 2024). "Furthermore, the major downstream kinase of ITGAV had been shown to be of diagnostic value as an independent prognostic factor in patients with liver cancer after surgery, predicting the survival outcome of patients." (PMID 40018050, 2025). "Firstly, we detected the expression level of ITGAV protein in clinical tissue samples from 5 patients with liver cancer, and found that the expression level of ITGAV in liver cancer tissues was positively correlated with the expression levels of CD68 (macrophage marker) and COL1A1 (CAFs marker)." (PMID 40018050, 2025). "In addition, ROC analysis showed that ITGAV, SPP1, COL4A2, and COMP had a potential diagnostic value for liver cancer patients." (PMID 38374893, 2024). "The risk score model constructed by genes (COMP, SPP1, COL4A2, and ITGAV) in the pathway of integrin cell surface interactions may be used to predict survival in liver cancer patients." (PMID 38374893, 2024). "It is indicated that the association between ITGAV, SPP1, COL4A2, COMP, and immune cells may be involved in the progression of liver cancer." (PMID 38374893, 2024). "This indicated that ITGAV may play important roles in tumorigenesis of liver cancer by activating the expression of BCL2, PXN and MAPK." (PMID 38374893, 2024). "It is suggested that ITGAV may play important roles in tumorigenesis of liver cancer by activating the expression of BCL2, PXN, and MAPK." (PMID 38374893, 2024). "In pathway of integrin cell surface interactions, COL4A2, COMP, ITGAV, and SPP1 were used to perform LASSO Cox regression analysis to construct the prediction model of the overall survival rate of liver cancer patients in the TCGA database." (PMID 38374893, 2024). "The mRNA expression levels of COL4A2, COMP, ITGAV, and SPP1 were significantly increased in liver cancer tissues." (PMID 38374893, 2024). "The RT-qPCR experiment was applied to further analyze the expression patterns of 3 key genes (COMP, ITGAV, and SPP1) in liver cancer patients who relapsed after 3 and 6 months." (PMID 38374893, 2024). "In order to explore the molecular mechanism by which ITGAV promotes tumorigenesis of liver cancer, the protein expression of BCL2, PXN, and MAPK was detected after overexpression and knockdown of ITGAV." (PMID 38374893, 2024).
thyroid cancer (4 papers, 2021 to 2025). "For most of the 39 cancers, there was no statistical correlation between ITGAV expression and TNM stage or clinical stage, except for adrenocortical carcinoma, LUAD, sarcoma, thyroid carcinoma, and LGG." (PMID 35927660, 2022). "The α2β1 complex is the one with higher upregulation in thyroid carcinomas (up to 9-fold for ITGA2 vs. 2.5-fold for ITGA3 and ITGAV), although it is not the most abundant integrin expressed." (PMID 34208249, 2021).
acute myeloid leukemia (3 papers, 2016 to 2022). Acute myeloid leukemia (AML) is a group of neoplasms arising from precursor cells committed to the myeloid cell-line differentiation. "Through an shRNA screen, an involvement of both ITGAV and ITGB3 was demonstrated in leukemogenesis using MLL-AF9 acute myeloid leukemia (AML) model." (PMID 36204266, 2022).
brain tumor (3 papers, 2013 to 2023). "Moreover, in brain tumors, ITGB8 and ITGAV integrins show the highest expression in primary proneural and mesenchymal gliomasphere cultures, while their interaction with the integrin-binding syalo-protein IBSP promote tumor cell migration." (PMID 37835469, 2023). "Next, we evaluate whether the high expressions of collagen type I receptors (ITGAV, ITGB8, SDC1, SDC4, and CD44) in tumor tissues, i.e., tumor receptors, are related with the prognosis of patients with brain tumor." (PMID 37479733, 2023).
colorectal tumor (3 papers, 2015 to 2023). "In a previous publication, our group identified an association between hyperexpression of the ITGAV gene in tumours and the presence of perineural invasion in colorectal tumours." (PMID 26674523, 2015). "In conclusion, a multivariate mathematical model was generated that demonstrated an association between hyperexpression of the integrins, ITGAV and ITGA6, and GS, and also between the ITGA3 integrin and DFS, in patients with colorectal tumours." (PMID 26674523, 2015). "Furthermore, the NID1 receptor ITGAV represents a candidate therapeutic target in CMS4 colorectal tumors." (PMID 38001576, 2023). "The final multivariate prognostic model achieved was composed of the ITGAV and ITGA6 integrins, which were found to correlate with GS, thereby suggesting that hyperexpression of these genes represents an independent action in reducing the survival of colorectal tumour patients." (PMID 26674523, 2015).
medulloblastoma (3 papers, 2015 to 2022). A malignant, invasive embryonal neoplasm arising from the cerebellum. "Compared to the normal cerebellum, the expression level of miR-192 in medulloblastoma cells is lower, and studies indicated that miR-192 suppresses the expressions of ITGAV, ITGB1, ITGB3, and CD47 in medulloblastoma." (PMID 35464451, 2022). "In medulloblastoma, miR-192 has been described as a suppressor of metastasis and inhibitor of cell adhesion to ECM components via integrins such as ITGB1 and ITGAV." (PMID 30473751, 2018). "After miR-192 transfection, there was a significant reduction in ITGAV, ITGB1, ITGB3, and CD47 in all miR-192-transfected medulloblastoma cells in comparison with NC miR-transfected cells (all P values <0.05)." (PMID 26506238, 2015). "In summary, this study revealed that the loss of miR-192 expression exerts wide ranging effects on cell proliferation and cell anchoring by activating DHFR and by molecular cross talk between ITGAV, ITGB1, ITGB3, and CD47 in the leptomeningeal dissemination of medulloblastoma." (PMID 26506238, 2015).